SIPA1L1 (signal induced proliferation associated 1 like 1)
Description:
Stimulates the GTPase activity of RAP2A. Promotes reorganization of the actin cytoskeleton and recruits DLG4 to F-actin. Contributes to the regulation of dendritic spine morphogenesis (By similarity).
Synonyms: E6TP1; KIAA0440; SPAR1
Tractability: Antibody: its Gene Ontology location is reachable by antibodies, with high confidence; the Human Protein Atlas places it where antibodies can reach. PROTAC: UniProt records ubiquitination sites on it; ubiquitination databases record sites on it; its protein half-life has been measured.
Gene: Protein-coding gene on chromosome 14 (71,320,277 to 71,741,230, forward strand). Ensembl gene ENSG00000197555.
Subcellular location: Cytoplasm, cytoskeleton; Postsynaptic density; Synapse, synaptosome
Subcellular location (Human Protein Atlas): Plasma membrane; Actin filaments
Pathways (Reactome):
Neuronal System: Neurexins and neuroligins
Gene Ontology:
Molecular function: protein binding; GTPase activator activity; ephrin receptor binding
Biological process: actin cytoskeleton organization; activation of GTPase activity; ephrin receptor signaling pathway; regulation of axonogenesis; regulation of dendritic spine morphogenesis; regulation of GTPase activity; regulation of synaptic plasticity; regulation of small GTPase mediated signal transduction
Cellular component: actin cytoskeleton; plasma membrane; dendritic spine; postsynaptic density; cytoskeleton; synapse
Genetic constraint (gnomAD): Loss-of-function variants: 25 observed, 154.22 expected, observed/expected ratio (o/e) 0.16, 90% interval 0.12 to 0.23. The upper end of that interval is the gene's LOEUF score, 0.23, which puts it in group 1 of 6, group 1 being the genes least tolerant of losing a copy. Missense variants: 1,842 observed, 2,292.8 expected, observed/expected ratio (o/e) 0.8, 90% interval 0.77 to 0.83. Synonymous variants: 810 observed, 864.93 expected, observed/expected ratio (o/e) 0.94, 90% interval 0.88 to 0.99.
Homologues: Orthologues: chimpanzee SIPA1L1 (99% identical), macaque SIPA1L1 (99% identical), pig SIPA1L1 (97% identical), guinea pig SIPA1L1 (97% identical), rat Sipa1l1 (96% identical), mouse Sipa1l1 (96% identical), dog SIPA1L1 (95% identical), rabbit SIPA1L1 (94% identical), tropical clawed frog sipa1l1 (78% identical), zebrafish sipa1l1 (60% identical), Drosophila melanogaster RapGAP1 (12% identical), Caenorhabditis elegans F53A10.2 (11% identical). Paralogues in human: SIPA1L2 (52% identical), SIPA1L3 (46% identical), SIPA1 (25% identical), GARNL3 (14% identical), RAP1GAP2 (13% identical), RAP1GAP (12% identical).
Diseases named in the same sentence as SIPA1L1 in open-access papers:
SIPA1L1 is named in the same sentence as 16 diseases in open-access papers, as found by Europe PMC text mining. Sharing a sentence is not in itself a finding about the gene and the disease. The quoted sentences say what the papers report.
Anxiety (2 papers, 2023 to 2024). Intense feelings of nervousness, tension, or panic often arise in response to interpersonal stresses. "Functional study has revealed that SIPA1L1 knockout can lead to hyperactivity and enhanced anxiety level in mice." (PMID 37277710, 2023). "It has been demonstrated in animal models that in Sipa1l1−/− knockout mice, lack of SPAR1 causes hyperactivity, increased anxiety, learning disabilities, social skills deficits, and susceptibility to epileptic seizures." (PMID 39640846, 2024).
liver fibrosis (2 papers, 2016 to 2024). "In regard to fibrosis, SIPA1L1 is expected to be an early detection indicator for liver fibrosis caused by carbon tetrachloride." (PMID 39361424, 2024). "In conclusion, the proteomic analysis of serum samples from CCl4-treated rats has enabled the identification of SIPA1L1 as a non-invasive marker of early liver fibrosis." (PMID 27230648, 2016). "The results were validated by ELISA in an independent group of 76 fibrotic/cirrhotic rats and 20 controls which confirmed SIPA1L1 as a potential non-invasive biomarker of liver fibrosis." (PMID 27230648, 2016). "In the liver, it has been reported that SIPA1L1 is an early indicator for liver fibrosis." (PMID 39361424, 2024). "Despite no studies having described the potential role that this protein may have in liver fibrosis, a previous investigation demonstrated that Wnt signaling affects the phosphorylation and stability of SIPA1L1." (PMID 27230648, 2016). "Since the Wnt signaling pathway is activated during liver fibrosis in hepatic stellate cells it is tentative to speculate that SIPA1L1 diminution is a consequence of the activation of the fibrogenic process." (PMID 27230648, 2016).
osteosarcoma (2 papers, 2021). A usually aggressive malignant bone-forming mesenchymal neoplasm, predominantly affecting adolescents and young adults. "Circ_SIPA1L1 induces osteosarcoma progression via the miR-379-5p/mitogen-activated protein kinase kinase kinase 9 (MAP3K9) pathway." (PMID 34592879, 2021). "circSIPA1L1 is a newly discoveredcircular RNA, which is formed by back-splicing of SIPA1L1 and is found increased in osteosarcoma (OS)." (PMID 33968929, 2021).
breast carcinoma (1 paper, 2022). "When missense variants were assessed, three further associations were observed for overall breast cancer (TMEM161A, SIPA1L1, ERCC2), and a further seven were observed for subtypes (RNF175, NCKAP1L, PHAX, SMARCA2, EML5, NTRK3, MED23)." (PMID 35884425, 2022). "The best putative candidates in this group were TMEM161A, ERCC2, and SIPA1L1 for overall breast cancer, RNF175 and NCKAP1L for ER-positive disease, and PHAX, SMARCA2, NTRK3, EML5, and MED23 for ER-negative disease." (PMID 35884425, 2022). "Analysis of rare missense variants identified evidence of associations of TMEM161A, SIPA1L1, and ERCC2 with overall breast cancer, RNF175 and NCKAP1L with ER-positive disease, and SLC22A10, PHAX, SMARCA2, EML5, NTRK3, and MED23 with ER-negative disease." (PMID 35884425, 2022). "There was modest evidence of an association with overall breast cancer risk for rare missense variants in three genes: TMEM161A (OR = 2.56 (CI 95% 1.19–5.51), p-value = 0.016), SIPA1L1 (OR = 1.68 (CI 95% 1.06–2.67), p-value = 0.026), and ERCC2 (OR = 1.45 (CI 95% 1.01–2.08), p-value = 0.047)." (PMID 35884425, 2022).
Cirrhosis (1 paper, 2016). A chronic disorder of the liver in which liver tissue becomes scarred and is partially replaced by regenerative nodules and fibrotic tissue resulting in loss of liver function. "Despite hemopexin failing to demonstrate its value as an indicator of cirrhosis, SIPA1L1 showed a clear serum diminution and a great accuracy at identifying early fibrotic stages in the validation group." (PMID 27230648, 2016). "Label free LC-MS/MS proteomic analysis resulted in the identification of two non-invasive independent circulating proteins, SIPA1L1 and hemopexin, biomarkers of fibrosis and cirrhosis, respectively." (PMID 27230648, 2016). "In particular, SIPA1L1 was down expressed in fibrosis whereas hemopexin was increased in cirrhosis." (PMID 27230648, 2016).
colorectal cancer (1 paper, 2021). A primary or metastatic malignant neoplasm that affects the colon or rectum. "Previous studies had confirmed SIPA1L1 to be strongly correlated with colorectal cancer and hereditary non-polyposis." (PMID 33968929, 2021).
fibrosis (1 paper, 2016). the formation of excess fibrous connective tissue in an organ or tissue in a reparative or reactive process. "In the current investigation, we observed a significant diminution of SIPA1L1 serum levels in mild/moderate fibrosis and this reduction was maintained over the fibrotic and cirrhotic groups." (PMID 27230648, 2016).
glaucoma (1 paper, 2024). Increased pressure in the eyeball due to obstruction of the outflow of aqueous humor. "Future studies pinpointing the exact molecular and cellular mechanisms of SIPA1L1 and its interaction with other modulating factors will be very important in the evaluation of this interesting protein and its potential clinical usefulness in the treatment of glaucoma." (PMID 39361424, 2024).
malignant meningiomas (1 paper, 2016). "On the other hand, SIPA1L1 has also been described as a potential tumor suppressor since it is located on a region in chromosome 14 which has been reported to exhibit a loss of heterozygosity in malignant meningiomas." (PMID 27230648, 2016).
SIPA1L1 also shares sentences with these, for which no sentence is quoted: angle-closure glaucoma (1 paper); cataract (1); diabetes (1); gastric cancer (1); liver disease (1); Stillbirth (1); tumor (1).